IL6 (interleukin 6)
Diseases named in the same sentence as IL6 in open-access papers (continued):
Sharing a sentence is not in itself a finding about the gene and the disease.
cancer (continued). "Pivotal mediators of cancer-induced cachexia are the transcription factors STAT3 and NF-κB, which, in turn, are mainly activated by the circulating pro-inflammatory cytokines, such as IL6 and TNFα, respectively." (PMID 32824440, 2020). "Furthermore, we found that cancer cells co-cultured with SCs expressed a higher level of the IL6 receptor (IL6R) and the IL6 signal transducer (gp130), respectively." (PMID 32308766, 2020). "Cancer cells lose receptor chain binding IL-6, and STAT3 is no longer expressed in cancer cell nests." (PMID 32308553, 2020). "In addition, activation of the LKB1/AMPK pathway by metformin which is the first-line treatment for type 2 diabetes, suppresses IL-6-induced STAT3 expression and NF-κB activation in various cancers." (PMID 31952344, 2020). "Under healthy physiological condition, adiponectin inhibits IL-6 and TNF and seems to have a functional interplay with IGF-1 that may be impaired in cancer patients." (PMID 32230855, 2020). "IL-6 is not cancer-specific and it has insignificant value to be considered as independent single diagnostic biomarker." (PMID 32961987, 2020). "Meanwhile, HSCs were cultured in cancer-CM with simultaneous TU-100 treatment (90: 90 μg/mL, 270: 270 μg/mL, and 900: 900 μg/mL), which were called as modified HSCs, and α-SMA and IL-6 mRNA expressions were significantly reduced in modified HSCs with TU-100 treatment (p < 0.05)." (PMID 33346211, 2020). "Additionally, CAF-derived cytokines like CCL5, IL6, and CXCL10 can promote the TCA cycle and thus favor the proliferation of cancer cells." (PMID 32422889, 2020). "In addition, Hao and collaborators showed that circulating adipose tissue-derived fatty acid binding protein 4 (FABP4) levels increase during obesity and can activate the axis IL-6/STAT3/ALDH1, thus driving cancer stemness." (PMID 33371274, 2020). "We have demonstrated that Oligo-Fucoidan reduces IL-6 and MCP-1/CCL2 expression and secretion in the ETO-treated cancer cells; thus, Oligo-Fucoidan may control autocrine loops in cancer cells and paracrine pathways in the innate and/or adaptive immune systems." (PMID 32059469, 2020). "IL-6 and YKL-40 are secreted by cancer cells and macrophages, and the latter also by neutrophils." (PMID 32756596, 2020). "In a previous study, we isolated four acyclic triterpenoids from A. katsumadai seeds and reported inhibitory effects on interleukin-6 (IL-6)-induced signal transducer and transcription 3 (STAT3) phosphorylation, which is a major mediator of inflammation and cancer." (PMID 32717961, 2020). "Leptin increases the expression of anti-apoptotic proteins, inflammatory markers (tumor necrosis factor, TNF-α, interleukin IL-6) and angiogenic factors (vascular endothelial growth factor, VEGF), all processes involved in cancer cell survival, proliferation and migration." (PMID 32854444, 2020). "Because activin A was important for IL‐6 secretion from the cancer cells in vitro, we tested whether the ActRII neutralizing antibody (CDD866) could reduce the level of IL‐6 in sera from TOV21G‐bearing mice." (PMID 31436048, 2020). "One important reason could be that IL-6, via stimulation of the STAT3 pathway, is a prominent growth factor of many cancer cells." (PMID 32864098, 2020). "In addition, MSLN enables cancer cell survival, despite inflammation, due to resisting TNF-α-induced apoptosis, through elevating Akt/PI3K/NF-kB and IL-6/MCL-1 axes." (PMID 33344222, 2020). "Cancer cell trans-endothelial migration was reduced when using flowed osteocytes conditioned medium, which was abolished when blocking intercellular adhesion molecule 1 (ICAM-1) and interleukin 6 in the medium." (PMID 31936342, 2020). "Pre- and postoperative serum levels of a panel of three inflammatory biomarkers YKL-40, IL-6, and CRP with the two cancer biomarkers CEA and CA19-9 showed that the patients with 2 or more elevated biomarkers had shorter RFS and OS after resection of liver metastases." (PMID 32756596, 2020).
cancer (continued). "In the exploration of the origins of breast CSCs and their relationships to non-stem cancer cells (NSCCs), a critical role for IL-6 has been found in controlling the dynamic balance between breast CSCs and NSCCs." (PMID 33123472, 2020). "Additionally, IL‐6 and IL‐11 activate STAT3 signalling, which works with NF‐κB to promote cancer development." (PMID 32347623, 2020). "Moreover, additive growth factors for tumorsphere formation, such as EGF and IL6, can phosphorylate STAT3 in cancer cells." (PMID 33023006, 2020). "In this positive loop which is known as a vicious cycle, cancer cells can augment osteoclast generation and activation directly by producing osteoclastogenic factors including RANKL, tumor necrosis factor (TNF)-α, IL-1, IL-6, and IL-11." (PMID 33050237, 2020). "IL6/STAT3/TWIST signaling pathway activation mediates esophageal squamous carcinoma EMT, whereas inactivation of STAT3 by an IL-6 inhibitor or siRNA-mediated downregulation of Twist enhances cancer cell apoptosis and reverses radiation-induced EMT." (PMID 32872659, 2020). "CAFs also contribute to M2 polarization by secreting multiple cytokines and stimuli including macrophage-colony stimulating factor, reactive oxygen species, IL-6, IL-8, CCL2, and CXCL6 as seen in multiple cancer model systems (e.g., PDAC, colorectal and esophageal squamous cell carcinoma)." (PMID 32957515, 2020). "Pin1 is highly expressed in a majority of cancers, and elevation in Pin1 levels by either OSM or IL-6 involves the activation of both STAT3 and NF-κB through direct binding with the pSer/Thr-Pro motifs of STAT3 and p65 in the nucleus that results in promotion of STAT3 transcriptional activation." (PMID 31952344, 2020). "Apart from having a proinflammatory effect, paracrine release of SASP factors such as IL-6 and IL-8 may induce epithelial-mesenchyme transition (EMT) and lead to cancer cell invasion." (PMID 32488850, 2020). "IL-6 signaling is one of the significant pathways identified in this study and has extensively been studied for its role in PDAC cachexia, and as a target for cancer therapy." (PMID 33334063, 2020). "With the cotreatment with LPS, which could boost the expression of cytokines in these cancer cells, berberine significantly reduced the increased expression of TNF-α and IL-6." (PMID 32258115, 2020). "The study assessed the level of IL-6 and the level of free fatty acids (FFA) to assess the effect of this cytokine on the breakdown of adipose tissue in the initial and advanced stages of cancer." (PMID 33327591, 2020). "In addition to their direct epigenetic action, BET proteins also coordinate an IL6-dependent AMPK nuclear signaling pathway converging on FoxO3, which contributes to cancer cachexia." (PMID 32635462, 2020). "IL-6/JAK/STAT3 and TGF-β signaling also participated in cancer inflammation and immunity." (PMID 33194678, 2020). "Arg1 and iNOS were the markers of MDSC population activation, and the activated MDSCs could secrete IL6, IL8, and IL10 to enhance cancer progression." (PMID 32195173, 2020). "Furthermore, the coculture of cancer cells with adipocytes results in FAO and an increased secretion of pro-inflammatory adipokines, such as IL-6, MCP-1 and IL-8." (PMID 32731620, 2020). "In survival analyses, cancer-specific prognostic impact was found for CRP, IL6, and IL1RA." (PMID 33066437, 2020). "Another therapeutic strategy would be targeting the paracrine signalling factors such as the CAFs-secreted TGF-β and CXCL12, and cancer cells derived PDGF-α/β, b-FGF, and IL-6 that could lead to CAFs activation." (PMID 33066013, 2020). "Under both conditions, of direct or indirect interactions between the cancer cells and monocytic cells, elevated levels of stemness, EMT or both were frequently mediated by inflammatory factors such as TNFα, IL-6 and/or ELR+ CXC chemokines that will be particularly mentioned in more detail later on." (PMID 33585241, 2020).
cancer (continued). "IL-6 and TNF-α increase due to cancer and it is thought that this increase induces neutrophils." (PMID 31122885, 2020). "Importantly, higher expression of stemness genes including interleukin (IL)-6, EpCAM and CD24 was observed in HCC with lnc-DILC downregulation, indicating a positive correlation between lnc-DILC downregulation and increased cancer stemness properties." (PMID 32231294, 2020). "IL-6, TNF-a and PGE2 produced by primary oral keratinocytes and carcinoma cells may induce oral mucosal inflammation." (PMID 31969157, 2020). "Although entirely conclusive results are not yet available, this evidence suggests the IL-6/JAK/STAT3 pathway as a potentially useful target for cancer treatment." (PMID 30925774, 2019). "DHTS deregulated the dynamic equilibrium from non-stem cancer cells to CSCs by dephosphorylating Stat3 and decreasing IL-6 secretion and inhibiting CSC formation." (PMID 31019654, 2019). "As a symptom of cancer cachexia, CRF is induced by various mediating factors, such as cytokines (tumor necrosis factor α (TNF-α), interleukin 1 (IL-1), IL-6, and interferon-γ (INF-γ)), hormones (insulin, glucagon, leptin, ghrelin, and adiponectin), and neuropeptide-Y." (PMID 31323874, 2019). "Collectively, IL-6, through the synergistic action of NF-κB and STAT3 TFs, together with the functions of miR-21, miR-181b-1, and let-7, establishes a feedback mechanism to sustain inflammatory signals to directly link chronic inflammation and cancer." (PMID 31557902, 2019). "As previously reported, our results confirm that IL-6 is sufficient to induce muscle FIS-1 expression in the absence of a cancer environment in vivo." (PMID 30918582, 2019). "Moreover, induction of IL‐6 and LIF by TGFβ has been reported in different types of fibroblasts including CAFs in other cancers." (PMID 31609088, 2019). "Elevated levels of inflammatory cytokines in a variety of tumors, e.g., IL-6, IL-1β, TGF-β and CXCL1, have shown positive correlations with radioresistance in cancer cells, whereas blocking the effects of these cytokines/chemokines can enhance sensitivity to RT." (PMID 31752313, 2019). "The ELISA and Western blot analyses revealed that neither co-culture with cancer cells nor 5-FU treatment increased the expression of IL-6 as well as NF-κB, a transcription factor for IL-6, in CAFs." (PMID 30927911, 2019). "Genomic and bioinformatic analyses of cells prepared from basal/squamous cell carcinoma, carcinoma of breast and melanoma demonstrated that simultaneous targeting of IL-6, VEGF-A and MFGE-8 (lactadherin), optionally with inhibition of IL-8, seems to be beneficial in cancer therapy." (PMID 30925774, 2019). "In particular, a cocktail mixture containing tumor necrosis factor-α (TNF-α), interleukin-1β (IL-1β), interleukin-6 (IL-6), and prostaglandin E2 (PGE2), is currently considered the gold standard for DC maturation and had been largely used in the context of anti-cancer therapeutic vaccines." (PMID 30621204, 2019). "It has been confirmed that EMT is a crucial step in the migration of cancer cells, which is controlled by different signaling transduction pathways and networks, such as autocrine IL11/IL6-gp130/JAK2/STAT, fibronectin-integrin, GAS6-Axl/Tyro3, PDGFR/FGFR/RET, and TGF-β R networks." (PMID 31126310, 2019). "Additionally, JAK/STAT3-mediated IL-6 phosphorylates mitogen-activated protein kinase (MAPK) and the Akt pathway, a major pathway in cancer proliferation." (PMID 31671670, 2019). "On the other hand, IL6 could activate STAT3, which was reported to promote the proliferation and metastasis of many cancers." (PMID 31709178, 2019). "Reduction of pro-inflammatory cytokines (e.g., IL-6, TNF-α, and IFN-ɣ) levels were observed when using the triple combination, which indicated that the synergistic drug combination was able to significantly control cancer progression." (PMID 31635311, 2019).
cancer (continued). "In addition to transcriptional effects, p38α can stabilize IL6 mRNA via multiple AREs in the 3′UTR of the IL6 transcript, and a role for TTP phosphorylation in this process has been established in cancer cells." (PMID 31394846, 2019). "In early clinical studies, some drugs have shown promising results by attenuating the symptoms of cancer cachexia even though they do not directly target the IL-6 pathway." (PMID 31010015, 2019). "NF-κB and STAT3 cooperatively regulate several cytokines and chemokines including IL-6 16, which alone activates STAT3 and generates an IL-6/STAT3/NF-κB positive-feedback circuit, which plays a role in chronic colorectal inflammation and cancer." (PMID 31754344, 2019). "Malaponte and colleagues demonstrated that IL-6 levels in plasma and monocyte samples were higher in cancer patients with DVT than in those without DVT." (PMID 32117207, 2019). "It has also been found that elevated CRP in cancer patients correlates with the expression of IL-6 and IL-6 receptors in cancer cells in the absence of apparent inflammation." (PMID 31038863, 2019). "In this sense, it has been reported that the oncogenic dysregulation of the RAS, MYC and the MAPK pathways in cancer cells contributes to the secretion of growth factors and cytokines such as VEGF, IL-6, IL-10, and IL-1β, leading to the recruitment and the tumorigenic transformation of macrophages." (PMID 31086100, 2019). "TRAIL treatment was also shown to enhance pro-inflammatory cytokine and chemokine production, including IL6, IL8, MCP1, CXCL1, and MIF, in various cancer cell types independent from TRAIL sensitivity although cytokines levels were higher in resistant cancer cells." (PMID 31333662, 2019). "We also found IFN-γ induced the overproduction of IL-6 and IL-8 through CEACAM1, which may take part in the pathogenesis of AECOPD or the transition from inflammation to cancer." (PMID 31072323, 2019). "Fibroblast-fibroblast connections can physically prevent cancer progression by three-dimensional networking and thus affecting ECM stability as well as by paracrine signaling, e.g., secretion of tumor necrosis factor α (TNFα) and IL-6." (PMID 31475157, 2019). "Importantly, IL-6/STAT3-mediated inhibition of miR-200c during transformation and EMT of breast and lung epithelial cancer cells has also been demonstrated by others." (PMID 31557902, 2019). "Evidence support DNA damage and stress induce sustained IL‐6 and IL1B production in PCa through P2Y11 receptor‐p38 MAPK‐NF‐κB signalling pathway, which may play an essential role in promoting cancer cells proliferation, survival, invasiveness and metastasis." (PMID 30592148, 2019). "Moreover, IL6 is involved in the cytokine-cytokine receptor interaction, the Jak-STAT signalling pathway, and pathways in cancer; therefore, it is closely related to imatinib resistance." (PMID 30909944, 2019). "Similarly, pro-inflammatory signals such as IL6 can cooperate with HH/GLI in promoting cancer growth via a molecular mechanism where GLI and the IL6/JAK2-activated transcription factor STAT3 bind and synergistically activate common HH-IL6 target genes." (PMID 30991683, 2019). "Furthermore, IL-1ß, IL-6 and TNF-α are present in the microenvironment of cancer, contributing to metastasis and drug resistance." (PMID 30923340, 2019). "While PDAC cancer cells, CAFs, and immune cells are all potentially responsive to TGFβ, it was an inflammatory subtype of CAF expressing PDGFRα that was consistently found to have highest expression of TGFβR2 and IL‐6." (PMID 31639254, 2019). "From this perspective, the IL-6/JAK/STAT pathway is nodal in novel therapeutic approaches for the preventive treatment of diseases including cardiovascular diseases, type 2 diabetes, cancer, and osteoporosis." (PMID 31114509, 2019). "Cancer inflammatory environment may be established by several factors, including pro-inflammatory cytokines such as TNF-α, IL-1β, and IL-6." (PMID 31252615, 2019).
cancer (continued). "Of these, the average expression of the two genes, including CD70 and PDCD1, and the 12 isoforms derived from the seven genes, including CD40, CD70, IL6, IL10, STAT1, STAT6, and TNFRSF14, were cancer immunotherapy-related genes (false discovery rate (FDR) < 0.01)." (PMID 31292525, 2019). "Further, we found that inhibition of TGFβR2 or IL‐6 had additive therapeutic efficacy only in vivo but not in vitro when IL6RA was knocked down in cancer cells." (PMID 31609088, 2019). "High levels of IL-6 have been reported in a lot of cancer patients and are also described as a potent negative regulator of dendritic cell maturation in vivo, contributing to control T cell-mediated immune responses." (PMID 31781335, 2019). "Cancer cells originating from the breast can form typical osteolytic metastases in the BM by secreting parathyroid hormone-related protein (PTHRP), tumor necrosis factor-α (TNFα), interleukin 6 (IL-6) and/or interleukin 11(IL-11)." (PMID 31817646, 2019). "Exercise plays a role in mediating the effects of chronic inflammation, reducing inflammatory markers such as C-reactive protein (CRP), tumor necrosis factor alpha, and various types of interleukin (IL), including IL6, in people with and without cancer." (PMID 31013573, 2019). "STAT3 is not only overexpressed and activated in cancer cells but also in tumor-associated immune cells, inducing the expression of immune-suppression related genes, including IL-6, IL-10, TGF-β and VEGF and driving the escape of cancer cells from immune-mediated elimination." (PMID 31088482, 2019). "Interestingly, IL-6 levels were significantly elevated in both genders, but FFA was only elevated in female cancer cachexia patients." (PMID 31788012, 2019). "Dying cancer cells induced by PS-PDT or PD-PDT emit calreticulin, HMGB1 and ATP and they were efficiently engulfed by BMDCs, which then matured, became activated and produced IL-6." (PMID 31842994, 2019). "Many inflammatory cytokines, such as IL-6 and IL-8, as well as MMP-2 and MMP-9, participate in regulating the inflammatory microenvironment and contribute to the increased migratory and invasive potential of hepatocytes, thus facilitating cancer metastasis." (PMID 31142326, 2019). "The niche of IL6 stimulates the expression of IGF-1R and autocrinal IGF1 dependently in HBV-HCCs and strongly correlates with OCT4/NANOG expression, early recurrence, and cancer stemness features." (PMID 31505803, 2019). "The IL-6/JAK1/2/STAT3 signaling pathway plays an important role in the conversion of non-stem cancer cells (NSCCs) into CSCs." (PMID 31019654, 2019). "For example, inhibitors of IL-6, IL-6 receptor, or Janus kinase (JAK) have already been approved by the US Food and Drug Administration for the treatment of myeloproliferative diseases and autoimmune disorders, with trials underway in cancer." (PMID 31462327, 2019). "In the experimental system that is modeled here, the only source of human IL-6 is the cancer cells themselves, as murine IL-6 does not bind to human IL-6R and cannot directly initiate signals on human cells." (PMID 29351275, 2018). "As expected, in mice that developed cancer IL-6 serum levels were higher compared to non-operated group." (PMID 29662006, 2018). "Nevertheless, IL-6 inhibitors showed no efficacy in large randomized trials of various cancers, in particular plasma cell cancers." (PMID 30064449, 2018). "As an alternative to paracrine IL6 signaling, activation of HH/GLI may itself stimulate the production of IL6 in the cancer cells." (PMID 29987839, 2018). "TLR4 ligation by PTX could activate downstream signaling via NF-κB and MAPK that promote pro-inflammatory mediators i.e. IL-6, IL-8, MCP-1, VEGF and XIAP, the functions of which have been reported to enhance cancer progression and drug resistance." (PMID 29486738, 2018). "Neutrophils treated with cancer supernatant upregulated TWIST and IL-6 genes in vitro." (PMID 29661142, 2018).